EQTN (equatorin)
Description:
Acrosomal membrane-anchored protein involved in the process of fertilization and in acrosome biogenesis.
Synonyms: AFAF; C9orf11; SPACA8
Tractability: Antibody: UniProt predicts a signal peptide or a membrane-spanning region; its Gene Ontology location is reachable by antibodies, with medium confidence; the Human Protein Atlas places it where antibodies can reach.
Gene: Protein-coding gene on chromosome 9 (27,284,654 to 27,297,150, reverse strand). Ensembl gene ENSG00000120160.
Subcellular location: Cytoplasmic vesicle, secretory vesicle, acrosome membrane; Cytoplasmic vesicle, secretory vesicle, acrosome inner membrane; Cytoplasmic vesicle, secretory vesicle, acrosome outer membrane
Subcellular location (Human Protein Atlas): Actin filaments; Plasma membrane; Predicted to be secreted
Gene Ontology:
Biological process: acrosomal vesicle exocytosis; endocytosis; fusion of sperm to egg plasma membrane involved in single fertilization
Cellular component: inner acrosomal membrane; outer acrosomal membrane; plasma membrane; acrosomal membrane
Genetic constraint (gnomAD): Loss-of-function variants: 17 observed, 14.39 expected, observed/expected ratio (o/e) 1.18, 90% interval 0.81 to 1.73. The upper end of that interval is the gene's LOEUF score, 1.73, which puts it in group 6 of 6, group 1 being the genes least tolerant of losing a copy. Missense variants: 279 observed, 264.67 expected, observed/expected ratio (o/e) 1.05, 90% interval 0.95 to 1.16. Synonymous variants: 96 observed, 96.22 expected, observed/expected ratio (o/e) 1, 90% interval 0.85 to 1.18.
Homologues: Orthologues: chimpanzee EQTN (98% identical), macaque EQTN (88% identical), mouse Eqtn (56% identical), dog EQTN (53% identical), rat Eqtn (49% identical).
Diseases named in the same sentence as EQTN in open-access papers:
EQTN is named in the same sentence as 1 disease in open-access papers, as found by Europe PMC text mining. Sharing a sentence is not in itself a finding about the gene and the disease. The quoted sentences say what the papers report.
Infertility (1 paper, 2022). "The deletion of C11orf94 leads to infertility in mice by affecting the expression of calcium pathway related proteins such as PDE1C, LGMN and ADD1, as well as sperm-oocyte fusion related proteins such as CRISP1, IZUMO1 and EQTN in mouse sperm." (PMID 36050562, 2022).